TNF (tumor necrosis factor)
Diseases named in the same sentence as TNF in open-access papers (continued):
Sharing a sentence is not in itself a finding about the gene and the disease.
infection (continued). "A major difference between early and late infection is the evolution of the immune response driven by the continuous release of immunomodulatory/inflammatory factors by the parasite, such as VSG and TSIF, which induce pathogenic TNF-α and IFN-γ while switching off the IL-10 production." (PMID 24204274, 2013). "In the present study, we genotyped SNPs of TNF, IFNG, IL6, IL10, and TGFB1 which are multifunctional cytokine that have been implicated in inflammation, immunity, and cellular organization and have been proposed to play important roles in infection and cancer biology." (PMID 23936772, 2013). "Mice double deficient for IL-1α plus IL-1β could not control the infection, similar to IL-1R1 deficient mice on day 35 post-infection, although bacterial burdens were not as high as those reached in TNF KO mice which succumbed at 4 weeks." (PMID 25400917, 2013). "TNF-α, however, is just one of the cytokines released in response to L. monocytogenes with other pro-inflammatory cytokines, including IL-6 and IL-1β, released during infection in vivo, and mast cells have been shown to secrete these in response to L. monocytogenes in vitro." (PMID 23460827, 2013). "In addition, blood samples were collected at 2, 6, 24 and 48 h post-infection to analyse the production of inflammatory cytokines such as TNF-α, IFN-γ, IL-6, keratinocyte chemoattractant (KC or CXCL-1, equivalent to human IL-8) and anti-inflammatory cytokine IL-10." (PMID 24107297, 2013). "However, TNF-α was significantly higher in the Lum−/− corneas by 2 days after infection." (PMID 23358433, 2013). "Furthermore, we show in arteriole remodeling and LN hypertrophy that eNOS, TNFα and mast cells to be contributing factors to the magnitude of remodeling and the LN arteriole to facilitate transient changes in NO levels through the course of infection." (PMID 23573281, 2013). "Thus, we determined the functionality of the epitope-specific CD8 T cells in the three groups of mice by intracellular cytokine staining (ICS) for the presence of IFNγ- and/or TNFα-producing cells and calculating the ratio of IFNγ+TNFα+/IFNγ+ cells at days 7 and 13 post infection." (PMID 24391647, 2013). "The infection may lead to activation of monocyte/macrophage lineage and expression of interleukin-6 (IL-6), interleukin-10 (IL-10), and tumour necrosis factor-alpha (TNF-α) the serum levels of which have been correlated with the severity of the infection." (PMID 23983770, 2013). "Other studies have indicated that epidermal growth factor (EGF), macrophage inflammatory protein (MIP)-1β, IL-1α, transforming growth factor (TGF)-α, soluble CD40 ligand (sCD40L), vascular endothelial growth factor (VEGF), IP-10, TNF-α, IL-12(p40), might discriminate between active TB and infection." (PMID 23691173, 2013). "IL-6, IL-1 and TNF-α are important cytokines in the immune response against Listeria, therefore their production by mast cells upon exposure to the bacteria may contribute to the immune defence against this infection." (PMID 23460827, 2013). "However, TNF-α production was significantly increased (P < 0.05) in peritoneal exudate (26.84 pg/mL± 2.91) and liver homogenate (190.30 pg/mL ± 23.90) from propolis-treated mice (10 mg/kg) after infection." (PMID 23762152, 2013). "Additionally, in these mice infection induced serum IL-15 and TNF-α expression." (PMID 23405155, 2013). "Importantly, most of the Mtb-infection induced IL-1β, IL-6, TNF-α and MCP-1 network genes were down regulated by PZA-treatment at both 42 and 63 days, while only 8–10% of these pro-inflammatory network genes were up-regulated, in all the four pro-inflammatory networks at both time points." (PMID 24015316, 2013). "In addition TNFα can be pro-viral by initiating infection through signalling to the MIE enhancer." (PMID 22952450, 2012).
infection (continued). "Infection with avirulent S. flexneri led to a substantial upregulation of only IL-22 (3.3 fold), although upregulation (1.4 fold) could also be detected for IL-17F and TNF-α." (PMID 22675469, 2012). "This primarily protective mechanism may become overshadowed by an acute pathophysiological response with the typical clinical symptoms of septic shock that frequently follows the release of inflammatory mediators, such as tumor necrosis factor (TNF)-a during infection." (PMID 23724321, 2012). "Potential of antibodies to TNF-α, IL-1RA, TNF-α soluble receptors and anti-bradykinin have also tested but it has been observed that treatment with such TLR inhibitors interfere with innate immunity of host against infection and consequently increasing the risk of shock and mortality." (PMID 22654663, 2012). "Moreover, IFN-γ and TNF production is impaired in these infection models." (PMID 22203861, 2012). "Our data are consistent with the possibility that TNF can prolong macrophage survival particularly in a hypoxic environment, such as a site of an inflammatory reaction, and perhaps have relevance for the proposed interdependence of the innate and hypoxic responses to tissue injury and infection." (PMID 23029275, 2012). "Therefore, we next ascertained the cytotoxic potential and the ability of PD-1high and PD-1medium CD8 T cells to produce pro-inflammatory cytokines like IL-2, IFN-γ and TNF-α when stimulated in vitro with immunodominant SSIEFARL peptide on day six post-infection." (PMID 22808056, 2012). "Interestingly, our lab found that Chinese highly pathogenic PRRSV (HP-PRRSV) infection failed to induce detectable IL-10 (unpublished data), but induced lower levels of TNF-α in PAMs." (PMID 22909062, 2012). "Furthermore, these results suggest that IFNγ may play a greater role in intestinal tissue injury while TNFα may be more involved in the systemic manifestations of infection." (PMID 23217055, 2012). "An infection of monocytes by CSFV could induce TNF-α secretion." (PMID 22253710, 2012). "While the TNFα transcript was not clearly up-regulated, either in resistant or in susceptible fish, the key pro-inflammatory cytokine IL1β was strongly induced by the infection." (PMID 22720048, 2012). "Also, it remains to be determined whether a specific pathogen gene in the context of an infection in vivo is capable of modulating levels of TNFα production." (PMID 22952450, 2012). "However, one animal (BD106) showed a high TNF-α plasma concentration before infection." (PMID 22533922, 2012). "However, despite the high production of this cytokine in the lesions associated to the clinical infection due to M. paratuberculosis, there are not leucocytes and neutrophils, and even the production of TNF-α is absent." (PMID 22151930, 2011). "In patients with particularly high risk (i.e. those patients with previous history of severe infection, low baseline HAI titers, and/or other co-morbidities) it may be reasonable to delay the next dose of anti-TNF drug to provide a longer window of developing a protective response." (PMID 22177419, 2011). "Thus, anti-TNF treatment either alone or in combination with MTX may contribute to reduced immune responses to infections and vaccination by limiting B cell responses and subsequent development of protective serum antibodies." (PMID 22177419, 2011). "However, in our case, although TNF-α is related to protection against infection, our finding of increased TNF-α mRNA expression in lesions of LTCP393(R)-inoculated mice five weeks post-infection, may be associated to Th2 responses." (PMID 21390155, 2011). "Therefore, we asked whether the expression of complement in moDCs could be regulated by mediators that can be generated during infection and tissue inflammation [i.e., LPS and TNF-α/IL-1/PGE2 (TIP)]." (PMID 21397947, 2011).
infection (continued). "However, it should be noted that TNF-α, C. novyi-NT infection, and doxorubicin-induced cancer cell apoptosis are all able to induce or enhance a host immune response that could have contributed to the observed therapeutic response." (PMID 21378416, 2011). "Thus, we evaluated the expression of TNFα by the fibroblasts at various times after infection." (PMID 22206025, 2011). "Therefore, to examine the possibility of TNF-mediated apoptosis of T1 and T2 transitional B cells, TNF−/− mice were infected with T. brucei and the number of T1 and T2 transitional B cells in the spleen was examined at different time points of infection." (PMID 21738467, 2011). "Thus, mice were neutralized of γδ T cells, TNF-α, or both, prior to infection with B. abortus." (PMID 21765931, 2011). "However, and consistent with that observed with MAR1-5A3 treatment at day 4 only with WNV-NY infection, the amounts of intracellular IFN-γ and TNF-α present in WNV-specific CD8+ T cells were lower (P<0.008) when type I IFN signaling was blocked throughout infection." (PMID 22144897, 2011). "For Ebola virus, infection-independent TNF-α activation has been suggested to occur in response to receptor cross-linking by the viral surface glycoproteins and, based on our observations, we can propose that a similar process may take place with arenavirus particles as well." (PMID 21572983, 2011). "Tumor necrosis factor (TNF-α) is a potent multi-functional cytokine produced by various cells, including neutrophils, activated macrophages, T and natural killer cells, and fibroblasts, in response to inflammation, infection, tissue injury and other environmental challenges." (PMID 21754991, 2011). "However, it is known that MHC class I molecules may be up-regulated in response to certain viruses and as well as soluble factors released during infections; such as type I and II interferons and TNF-α." (PMID 21179539, 2010). "Also, depletion of IFN-γ or TNF-α at the time of infection abolished vaccine mediated protection." (PMID 21085470, 2010). "Interestingly, C57Bl/6 BMDM do not undergo apoptosis upon infection with non-pathogenic mycobacteria despite the fact that they still induce an increase in TNF secretion." (PMID 20831789, 2010). "Nlrp3−/− mice had a modest but statistically significantly increase in IL-6 and TNF-α cytokines at 2 weeks (p = 0.026 and p = 0.028, respectively) and 5 weeks post-infection (p = 0.004, p = 0.001, respectively), but all differences were diminished by 16 weeks post-infection." (PMID 20808838, 2010). "Steroids are a classic risk factor of infection in RA patients exposed or not to TNFα blockers." (PMID 20637100, 2010). "This agrees with data from the Swedish practice-based registry ARTIS (AntiRheumatic Therapies In Sweden), which indicate that there is a slight increase in the risk of infection in RA patients treated with anti-TNF-α agents but that it is not driven by any particular type of infection." (PMID 20569501, 2010). "Some studies concluded a similar risk of postoperative infection after orthopedic surgery whether the patients were exposed or not to TNFα blockers, whereas other studies highlighted a higher risk with TNFα blockers reaching a two-fold increase." (PMID 20637100, 2010). "However, more recently, it wasreported that substantial infection of adipocytes could take place when TNFα was present in the medium." (PMID 19081837, 2009). "By contrast, G-CSF, TNF, and MCP-1 levels in the kidneys at 24 and 48 h showed associations with lesion parameters at both times, possibly indicating involvement of these effectors in the progression of infection subsequent to the neutrophil-recruiting early activities of KC, IL-6 and MIP-1β." (PMID 19641609, 2009).
infection (continued). "The quantitative effect of this infection was large, with modelling results indicating that the highest levels of louse reproductive activity (>20 louse egg cases per host) were associated with approximately 50% reductions in TLR2 and TLR9-mediated TNF-α responses." (PMID 19386086, 2009). "The pro-inflammatory cytokines IL-1β, TNF-α and IL-6, which are readily induced by the presence of lipopolysaccharides from Gram-negative bacteria play an important role in the synthesis of acute phase proteins and often participate in the pathogenesis of many infections." (PMID 18700003, 2008). "However, the peak of TNFα expression in the pancreas is around day 7 post-infection." (PMID 23675028, 2007). "In HSV-infected macrophages exposed to IFN-γ, iNOS is induced synergistically though TNF-induced NF-κB activation and translocation to the nucleus, as shown by binding of a heterodimeric complex of p55/p65 and a homodimer of p55 to the κB-site of the iNOS promoter during infection." (PMID 16076403, 2005). "Finally, the question arises why mem-TNF mice succumb in the chronic phase of infection." (PMID 16285886, 2005). "Therefore, sustained membrane expressed TNF on myeloid and lymphoid cells may be necessary to control infection." (PMID 16285886, 2005). "Therefore, membrane TNF is sufficient for granuloma formation and infection control." (PMID 16285886, 2005). "We identified interferon (IFN)-α and tumour necrosis factor (TNF)-α as potential mediators of AML cytotoxicity, and SMAC/BH3 mimetics enhanced AML cell death following direct OV infection, indicating autocrine-paracrine signalling events." (PMID 41963598, 2026). "The abundance of Proteobacteria exhibited a positive correlation with rectal temperature at both 12 and 24 h post-infection, as well as with serum TNF-α levels and jejunal IL-1β and TNF-α mRNA levels." (PMID 41547922, 2026). "During the early stages of infection, macrophages initiate a cytokine cascade by producing IL‐12, which stimulates natural killer (NK) cells to secrete interferon‐gamma (IFN‐γ), TNF‐α, and NO, thereby enhancing parasite clearance." (PMID 41573114, 2026). "Infections with lethal strains such as 17XL often trigger massive production of pro‐inflammatory cytokines like IFN‐γ and TNF‐α, leading to systemic inflammation and tissue damage." (PMID 41461395, 2026). "The relative expression of IL-6, IL-10, TNF-α, and IFN-α in the livers of infected mice significantly increased after BVDV infection, indicating that the infection triggers an inflammatory response in the host." (PMID 41514840, 2026). "Infection disrupts pro-inflammatory cytokine balance (e.g., IL-6, IL-1β, IL-8, IL-10, IFN-γ, TNF-α), promoting leukocyte accumulation and inflammation." (PMID 41602759, 2026). "Upon re-infection, healed PTX3-/- mice produced significantly more IL-17A, while levels of IFN-γ, TNF-α, and IL-10 were similar." (PMID 41743710, 2026). "triangularis infection-related proteins, highlighting hub genes such as AKT1, TNF, MMP9, CDK1, and PIK3C3, and enriched pathways in autophagy, immune regulation, oxidative stress responses, and kinase-mediated signaling." (PMID 41993607, 2026). "Levels of inflammatory cytokines IL‐1β, IL‐6, IL‐8, IL‐10, IL‐12/23p40, TNF‐α, and HMGB1 were significantly upregulated by infection with S. Typhimurium in the LT2 group." (PMID 41474380, 2026). "For context, the anti-TNF comparator cohort had a crude SAE rate of 13.3 per 1,000 patient-years (95% CI: 10.6–16.5) and a serious infection rate of 49.1 per 1,000 patient-years (95% CI: 43.8–54.8)." (PMID 42015260, 2026).
infection (continued). "Key proinflammatory cytokines-interleukin (IL)-1β, tumor necrosis factor (TNF)-α, and interferon (IFN)-γ-were elevated in the cecum during early infection but declined in the spleen during later phases." (PMID 42204750, 2026). "During early stages of infection, RSV activates the PI3K-Akt pathway to induce cFLIP expression, effectively suppressing TNF-driven extrinsic apoptosis." (PMID 41576161, 2026). "The infection also elicited a dynamic cellular immune response, marked by biphasic IFN-γ production and dose-dependent increases in IL-17A and TNF-α." (PMID 41751072, 2026). "In non‐lethal infections, early production of pro‐inflammatory cytokines such as IFN‐γ and TNF‐α supports parasite control, while timely induction of regulatory cytokines like IL‐10 and TGF‐β prevents excessive inflammation." (PMID 41461395, 2026). "By 48 h post infection, both hBMECs and NCC-PCs showed strong upregulation of inflammatory signaling pathways, including IFN-α and IFN-γ responses and TNFα signaling." (PMID 41541694, 2026). "Knockdown of FCGBP in goat bronchial epithelial cells leads to impaired cellular barrier function, resulting in excessive activation of type I interferon, HIF-1, TNF, and NOD-like receptor signaling pathways following infection with P." (PMID 41847354, 2026). "Compared to the control group, the protein expressions of TNF-α, IL-1β, and IL-6 in the GPS infection group were significantly higher (p < 0.01)." (PMID 40867785, 2025). "These included interferons (IFN-α, IFN-β, and IFN-γ), proinflammatory factors (IL-1β, IL-6, and TNF-α), the anti-inflammatory cytokine (IL-10), and matrix metalloproteinases 3 (which contribute to blood-brain barrier disruption) after TMUV infection." (PMID 40401981, 2025). "Understanding how TNF-α signalling is altered in PMM2-CDG and its interplay with infections is crucial for advancing clinical care." (PMID 41050669, 2025). "We analysed mRNA expression of 9 inflammatory markers (TGF-β1, TNF-α, IL-1β, IFN-γ, IL-6, IL-23, IL-17a, iNOS and ColA1) in kidney of experimental mice at 15 days post infection." (PMID 40445994, 2025). "Our results showed that baicalin reduced the expression of the pro-inflammatory cytokines tumor necrosis factor alpha (TNF-α), interleukin-1 beta (IL-1β), and interleukin-6 (IL-6) in PPMCs and the peritoneum of piglets after GPS infection." (PMID 40867785, 2025). "Endothelial cells in mice choroid plexus are invaded by T. gondii before the infection of the BBB, leading to an upregulation of IFN-γ, TNF-α, IL-6." (PMID 40743275, 2025). "Pro-inflammatory cytokines, including IL-6 and tumor necrosis factor-alpha (TNF-α), directly enhance PCT expression, a process that can occur independently of infection." (PMID 40963340, 2025). "While TNF contributes to viral clearance early in infection, as shown for influenza virus and RSV, excessive TNF, together with IFN-γ, can drive cell death, tissue damage, and mortality, as demonstrated in SARS-CoV-2 infection." (PMID 41346628, 2025). "The results showed that in the rVSV-WT group, the levels of TNF-α, IFN-γ, and CCL4 were significantly higher at 24 h post-infection compared to the rVSV-M2 and rVSV-M4 groups." (PMID 40872776, 2025). "Ahsg (also termed fetuin-A) belongs to the ‘acute phase proteins’ (APPs), and its expression is negatively regulated by several pro-inflammatory cytokines such as TNF, IL-1, IL-6 and IFN-γ during infection or other inflammatory illnesses." (PMID 41009783, 2025). "During the blood infection stage, pro-inflammatory cytokines such as IL-1β, IL-6, IL-8, IL-12, IFN-γ, and TNF-α released by the host immune system play a decisive role in antimalarial immunity by regulating immune cell activation and pathogen clearance." (PMID 41422632, 2025). "The levels of proinflammatory cytokines including TNF, IL-1β, IL-6, and MIP-2 were measured in the cell-free supernatants of the P. aeruginosa-infected BMDMs at 3 h post-infection." (PMID 40143103, 2025).